SLC1A5 (solute carrier family 1 member 5)
Diseases named in the same sentence as SLC1A5 in open-access papers (continued):
Sharing a sentence is not in itself a finding about the gene and the disease.
cancer (continued). "SLC1A5 was a protective factor in terms of DSS in LUSC and PCPG patients, but the trends for OS and DSS were consistent for all other cancer types." (PMID 37566748, 2023). "SLC1A5 and SLC7A5 have been proposed as critical therapeutic targets in cancer metabolism due to their significance in tumor metabolism." (PMID 37161350, 2023). "Whereas KP enzymes preceding KMO, and also the 2 Trp transporters SLC1A5 and SLC7A5, are up-regulated in 32-46% of cancer types, KMO and subsequent enzymes show lesser expression, ranging from 3 to 18%." (PMID 36286592, 2022). "SLC1A5 and SLC7A5 have been identified as potential therapeutic targets in cancer metabolism because of their significance in tumor metabolism." (PMID 35757505, 2022). "The upregulation of solute carrier family 1 member 5 (SLC1A5), a glutamine transporter, has also been observed in many cancers." (PMID 35847989, 2022). "Alanine-serine-cysteine transporter 2 (ASCT2), also named SLC1A5, is a major glutamine transporter overexpressed in many cancers." (PMID 35732988, 2022). "Many studies had reported that cancers vastly demand amino acid for ATP yielding, growth, and progression, through overexpression of SLC7A5 and SLC1A5." (PMID 34789172, 2021). "Cancer cells take up glutamine via glutamine transporter (ASCT2), also known as solute carrier family 1 member 5 (SLC1A5)." (PMID 35004688, 2021). "SLC1A5 also known as ASCT2, is neutral amino acid transporter and often found to be overexpressed in cancer cells." (PMID 33717005, 2021). "In previous studies, the glutamine transporters SLC1A5, SLC7A5, SLC7A11, and SLC3A2 were found to be highly expressed in a variety of cancers." (PMID 34573287, 2021). "L-g-glutamyl-p-nitroanilide is an inhibitor of SLC1A5 that leads to GLN starvation in cells and inhibits GLN-dependent mTOR activation, thus suppressing cancer progression." (PMID 34503536, 2021). "c-Myc was shown to bind the promoters of SLC1A5 and SLC7A5 genes and upregulate their expression in cancer cells, indicating that c-Myc acts to sustain amino acid uptake through these transporters." (PMID 33953707, 2021). "Amino acid transporters are upregulated in the different types of cancer, and many of them, such as CD98hc/SCL3A2, LAT1/SLC7A5, ASCT2/SLC1A5, emerged as promising molecular biomarkers, therapeutic targets, and novel tools for tumor imaging." (PMID 33401748, 2021). "In this study, we systematically analyzed the gene expression, epigenetic regulation, and genomic alterations of six key GLNM regulators (including SLC1A5, SLC7A5, SLC3A2, SLC7A11, GLS, and GLS2) across 33 different cancer types." (PMID 34573287, 2021). "To date, there are two different AATs (SLC1A5/ASCT2 and SLC7A5/LAT1) that have been reported to play important roles in the progression of different types of human cancers through mTOR activation." (PMID 34003553, 2021). "Collectively, our data reveal that oncogenic KRAS alters the expression of AATs such as SLC1A5/ASCT2, SLC7A5/LAT1, and SLC38A2/SNAT2 and thereby increase the uptake of AAs to support cancer cell proliferation through mTOR activation." (PMID 34003553, 2021). "ASCT1 (SLC1A4) and ASCT2 (SLC1A5) transporters exhibited high expression in most cancer cell lines, with the exceptions of ASCT1 and ASCT2 that were virtually undetectable in MiaPaCa-2 or Capan-2, respectively." (PMID 33801101, 2021). "For example, the alanine–serine–cysteine transporter 2 (ASCT2), otherwise known as SLC1A5, and SLC38A2 (SNAT2), are the primary transporters responsible for glutamine uptake in cancer cells." (PMID 34541580, 2021). "Among them ASC family transporter 2 (ASCT2, also known as SLC1A5) is generally up-regulated in human cancers and involved in metabolic reprogramming." (PMID 35003365, 2021).
cancer (continued). "To date, four distinct amino acid transporters have received increasing attention for their role in the promotion of cancer: SLC1A5 (also known as ASCT2), SLC7A5 (also known as LAT1), SLC7A11 (also known as xc−), and SLC6A14 (also known as ATB0,+)." (PMID 33806675, 2021). "One of the glutamine transporters that has caught attention is ASCT2/SLC1A5, which is an amino acid exchanger that mediates the Na+-coupled influx of glutamine into cancer cells in exchange for Na+-coupled efflux of some other neutral amino acid." (PMID 33019627, 2020). "The transporters capable of importing glutamine such as ATB0,+ (SLC6A14 gene), SNAT1 (SLC38A1 gene), ASCT2 (SLC1A5 gene), LAT1 (SLC7A5 gene), and LAT2 (SLC7A8 gene) are crucial in cancer metabolic remodeling often being upregulated in tumors." (PMID 32993063, 2020). "Data from the DepMap database show high expression levels of SLC1A5, SLC7A11, SLC38A2, and SLC7A5 in the selected cancer cell lines." (PMID 33400734, 2020). "Glutamine can be taken up by cancer cells via a number of different amino acid transporters, among which ASCT2 (alanine/serine/cysteine transporter 2, coded for by the SLC1A5 gene) is the best described." (PMID 31096630, 2019). "We demonstrated that the uptake of glutamine by amino acid transporter (SLC1A5), as well the metabolism of glutamine to glutamate by glutaminase (GLS) was upregulated in the cancer epithelia in response to elevated concentrations of glutamine in the media." (PMID 31627186, 2019). "Alanine-serine-cysteine transporter 2 (ASCT2, SLC1A5) is the primary transporter of glutamine in cancer cells and regulates the mTORC1 signaling pathway." (PMID 31580259, 2019). "Microarray data pointed to elevated expression levels of SLC1A5 (ASCT2) and SLC7A5 (LAT1) in many cancers, which since has been confirmed in many studies and cell lines." (PMID 30072900, 2018). "Accordingly, oncogenic transformation frequently up-regulates the expression of transporters such as the solute carrier family 1 member 5 (SLC1A5/ASCT2), a Na+-coupled amino acid transporter whose main function in cancer cells is glutamine uptake." (PMID 29865240, 2018). "Up-regulation of SLC1A5 (ASCT2) and its clinical significance has been reported in a variety of human cancers." (PMID 28749408, 2017). "Due to the upregulation of SLC1A5 and LAT1 in a wide spectrum of human cancers, both transporters are currently being investigated as therapeutic targets." (PMID 28553292, 2017). "Solute Carrier Family 1, member 5 (SLC1A5), also named as ASCT2, belongs to system ASC and performs as a high-affinity glutamine transporter in cancer cells." (PMID 26599282, 2015). "SLC1A5 functionally couples with SLC7A5 and promotes mTOR activation in cancer cells." (PMID 40362545, 2025). "SLC1A5, SLC3A2, and SLC7A5 are upregulated in various cancer types, which underpins the increased demand for bulk protein synthesis owing to the enhanced proliferation of cancer cells." (PMID 39757767, 2025). "The unveiling of SLC1A5, SLC7A5, SLC6A14, and the SLC38 family transporters, along with their distinctive functional characteristics, enriches our comprehension of the intricate nature of glutamine transport in cancer." (PMID 38459595, 2024). "Therefore, the upregulation of SLC1A5 inhibits the production of MDA and upregulates GPX4 to reduce oxidative stress-related damage, thereby accelerating cell proliferation and promoting malignant tumor progression." (PMID 37566748, 2023). "Remarkably, IGF2BP2 governs glutamine uptake and metabolism by upregulating MYC, glutamic-pyruvic transaminase 2 (GPT2), and solute carrier family 1 member 5 (SLC1A5) in AML, which indicates that IGF2BPs could regulate amino acid metabolism in cancers." (PMID 37554271, 2023).
cancer (continued). "Cancer cells upregulate multiple amino acid transporters as a means to increase the influx of amino acids from circulation; this includes the transporters SLC7A5 (LAT1), SLC1A5 (ASCT2), SLC6A14 (ATB0,+), SLC7A11 (x-c), SLC38A5 (SNAT5) and SLC43A2." (PMID 36765717, 2023). "Our GSEA results showed that SLC1A5 was involved in immune activation processes, such as TNFA signaling via NFKB, IFN-α response, IFN-γ response, and inflammatory response, but this correlation was quite different in different cancer types." (PMID 37566748, 2023). "Finally, Cluster 3 is characterized by up-regulation of SLC1A5 and SLC7A5 that promotes cancer cell dependence on glucose and increases the need of cytosolic NADPH sustained by concomitant up-regulation of G6PD." (PMID 36083313, 2023). "Moreover, overexpression of the tryptophan-transport- and metabolism-related genes SLC1A5, SLC7A5, SLC7A8, and TDO2 in tumor cells also provides potential strategies for cancer therapy." (PMID 37545500, 2023). "For ITGA2, SLC1A5, TIAM1, TNIK, and ABTB2, several studies showed that their high expression played a significant role in promoting tumor cell growth and inhibiting cell apoptosis from chemotherapy in different kinds of cancers." (PMID 35267472, 2022). "SLC1A5 and SLC38A1 cotransport polarized Na+ and glutamine, and SLC1A5 has been identified as amino acid harmonizer, whereas SLC38A1 has been recognized as an amino acid loader in cancer cells." (PMID 36262284, 2022). "SLC1A5 preferred to fulfill the proliferative demands from cancer cells rather than promoting ferroptosis to restrict PAAD progression." (PMID 35419359, 2022). "In cancer carbon metabolism pathways, the Warburg effect obviously appeared in HSCC; glycolysis-related gene HK, PKM, and LDHA were upregulated; and transporter genes GLS, SLC1A5, MCT4 and GLUT1 were upregulated." (PMID 36090994, 2022). "The transcription factor MYC, one of the most frequently amplified genes in human malignancies, is a master-regulator of amino acid metabolism promoting the expression of transporter proteins such as SLC1A5, SLC7A5 and SLC43A1 and thus, driving cancer growth by effective amino acid delivery." (PMID 33401748, 2021). "Second, despite the finding that SLC1A5 expression correlates significantly with immune cell infiltration in LGG and HCC, there was no database reflecting the correlation of SLC1A5 expression and immunotherapeutic response in these cancer types." (PMID 34367941, 2021). "Since the circRNAs hsa_circ_0051620| SLC1A5 and hsa_circ_0066954| POLQ interact with CDH2, they might have a prognostic value in cancer." (PMID 34055888, 2021). "A high level of glutamine transporter (SLC1A5) and glutaminases (GLS), two key factors involved in the conversion of glutamine into glutamate supplying nitrogen for anaplerotic flux to TriCarboxylic Acid (TCA) cycle, was detected in c-myc driven cancers." (PMID 34663785, 2021). "Since SLC1A5, SLC3A2, and SLC7A5 are important for the metabolism, growth, and proliferation of cancer cells, these transporters have been targeted pharmacologically to block cancer cell growth and survival." (PMID 33953707, 2021). "SLC1A5 is mainly involved in GLN import into cells, leading to cancer cell proliferation." (PMID 34503536, 2021). "ASCT2 (SLC1A5) and LAT1 (SLC7A5) are two transporters commonly over-expressed in cancers." (PMID 32821346, 2020). "Notably, SLC1A5 is also a target for c-MYC111,112, implying that cancer cells induce the two transporters (LAT1 and ASCT2) in a coordinated manner to enhance the functional coupling necessary for proliferation." (PMID 31980738, 2020). "While the exchange transporter ASCT2, coded by SLC1A5, has been widely found overexpressed in numerous cancer cell models, the so called System A and System N transporters, members of the SLC38 family are considered the principal unidirectional transporters for the amino acid." (PMID 32164327, 2020).
cancer (continued). "We postulate that other AA transporters, such as ASCT1 (SLC1A4) and ASCT2 (SLC1A5), might be more important for serine uptake in MCF7 cancer cells." (PMID 31152137, 2019). "The transporters for glutamine and essential amino acids, ASCT2 (solute carrier family 1 member 5, SLC1A5) and LAT1 (solute carrier family 7 member 5, SLC7A5), respectively, are overexpressed in aggressive cancers and have been identified as cancer-promoting targets." (PMID 29326164, 2018). "Glutamine is transported by several families of amino acid transporters, of which ASC amino-acid transporter 2 (ASCT2), also named solute carrier family 1 member 5 (SLC1A5), belongs to the most ubiquitously expressed glutamine transporters in human cancer cells." (PMID 29020998, 2017). "For example, SLC1A5 takes up l-glutamine which is then exchanged for mTOR-activating l-leucine and other essential amino acids via the bidirectional antiporter SLC7A5, and both SLC1A5 and SLC7A5 are overexpressed in cancers along with glutamine transporter, SLC6A14." (PMID 28350329, 2017). "Solute Carrier Family 1, member 5 (SLC1A5), also named as ASCT2, a major glutamine transporter, is highly expressed in various malignancies and plays a critical role in the transformation, growth and survival of cancer cells." (PMID 26599282, 2015). "REVs were found to enhance the expression of CAFs related proteins like αSMA, CD95, EMT marker vimentin, SLC1A5, and STAT3 phosphorylation as well as FAP expression after 48 hours exposure to REVs and SEVs suggesting that REVs can subvert stromal fibroblasts to adopt a cancer-promoting phenotype." (PMID 39431017, 2024). "In addition to integrins, we identified other glycoproteins regulated by B4GALT1, such as neutral amino acid transporter (SLC1A5), insulin receptor (INSR), and growth/differentiation factor 15 (GDF15), which have been reported to modulate cancer malignant phenotypes." (PMID 37907465, 2023). "Although the relationship between SLC1A5 and parthenolide in the treatment of cancer has not yet been elucidated, our findings and deduced hypotheses can provide some clues for further research." (PMID 37566748, 2023). "However, the regulatory roles of SLC1A5 in cancer are not straightforward; it is a double-edged sword in cancer progression." (PMID 35419359, 2022). "In sum, we speculated that glutamine transported by SLC1A5 is preferentially applied to fulfill the demands of cancer cell proliferation rather than synthesizing the precursor of ferroptosis." (PMID 35419359, 2022). "The interplay between SLC1A5 and SLC7A5, belonging to the SLC7 family of glutamine antiporters, was previously suggested, pointing towards the enhanced entry of essential amino acids via SLC7A5, activated by Gln flux through SLC1A5, as a strategy contributing to cancer progression." (PMID 35158820, 2022). "Therefore, both SLC1A5 and SLC7A11 are potential drug targets for cancer therapy." (PMID 34503536, 2021). "Thus, our data unveil the upregulation of the selected AATs (SLC1A5/ASCT2, SLC7A5/LAT1, and SLC38A2/SNAT2) as a prognostic marker of poor survival of patients with CRC, useful for cancer patient stratification, in particular with regard to the KRAS mutant subtype of patients." (PMID 34003553, 2021). "In addition, GW501516 increases expression of glucose transporter 1 (Glut-1) and solute carrier family 1 member 5 (SLC1A5), which results in an increased influx of glucose and glutamine in different cancer cell types and subsequently augments cancer cell proliferation." (PMID 32375405, 2020). "SLC1A5 might not be an appropriate target for suppressing glutamine uptake by cancer cells because it is not the only plasma membrane glutamine transporter, and its function would therefore be compensated by other redundant glutamine transporters such as SLC38A1 and SLC38A2." (PMID 32943735, 2020). "Although several studies evaluated the function of SLC7A11 and SLC1A5, the role of some SLC proteins in cancer is not studied well." (PMID 38705513, 2024).
cancer (continued). "The results showed that apart from EPAS1 and RAD51AP1 that without immunohistochemistry data, SQLE, CAPG, RRM2, SLC1A5, and SRC as dangerous genes were higher expressed in cancer tissues." (PMID 37461802, 2023).
tumor (329 papers, 2009 to 2026). "Only PCYR1 was associated with SLC1A5 in luminal B tumours, suggesting that the primary source of Gln in these tumours is via uptake rather than neosynthesis." (PMID 39843491, 2025). "Amino acids require specific transporters to facilitate their role on mitochondria, but senescent cells cause mutations in their transporter SLC1A5, promoting tumor metabolic reprogramming." (PMID 40046406, 2025). "A significant association was also observed between high SLC1A5 expression and medullary-like tumours (P < 0.001)." (PMID 39843491, 2025). "High SLC1A5 mRNA expression was significantly associated with larger tumour size, higher grade and nodal stage together with poor NPI (all P < 0.001)." (PMID 39843491, 2025). "Both high SLC1A5 mRNA and SLC1A5 protein expression were associated with larger tumour size, higher grade, and positive axillary lymph node metastases (P < 0.01)." (PMID 39843491, 2025). "Meanwhile, the upregulation of SLC1A5 in CRC tissues was significantly associated with enhanced tumour growth and survival." (PMID 41154605, 2025). "Many amino acid transporters were significantly associated with SLC1A5 expression, primarily in TN tumours and, to a lesser extent, in luminal tumours (P < 0.05)." (PMID 39843491, 2025). "SLC1A5 CN gains were observed in 3% and CN loss in 2% of invasive BC patients, whereas high SLC1A5 mRNA expression was observed in 61.4% of the tumours." (PMID 39843491, 2025). "The associations of SLC1A5 mRNA with ER- and PR- tumours, as well as with HER2 + basal and luminal B tumours (PAM50), were confirmed using bc-GenExMiner." (PMID 39843491, 2025). "The prognostic role of SLC1A5 also was assessed in stomach adenocarcinoma and its association with tumor-infiltrating immune cells and immune checkpoints in the tumor microenvironment (TME) was revealed." (PMID 38705513, 2024). "SLC1A5 expression was revealed to be associated with immune response, while silencing SLC1A5 negatively affects proliferation and invasion, and decreases the infiltration and M2 polarization of tumor-associated macrophages." (PMID 38705513, 2024). "Higher KIRC SLC1A5 or MTHFD2 expression levels were associated with higher tumor stages, increased lymph node metastasis possibilities, poorer OS, and poorer RFS." (PMID 39958609, 2024). "Higher SLC1A5 or MTHFD2 expression levels were associated with higher KIRC tumor stage and higher KIRC lymph node metastasis likelihood." (PMID 39958609, 2024). "High levels of SLC1A5 were associated with poor overall survival, poor disease specific survival and tumor progression." (PMID 36902506, 2023). "In this work, we discovered that the high expression level of SLC1A5 was associated with poor overall survival, poor disease specific survival, tumor progression and immunosuppression." (PMID 36902506, 2023). "Next, the correlations of the SLC1A5 expression level with immunotherapy response, immunomodulator expression, tumor mutation burden (TMB) and microsatellite instability (MSI) were evaluated." (PMID 37566748, 2023). "High SLC1A5 expression is associated with poor overall survival, as well as increased numbers of tumor-infiltrating B cells, CD4+ T and CD8+ T cells, macrophages, neutrophils and dendritic cells." (PMID 36902506, 2023). "The amino acid transporter SLC1A5 (ASCT 2) is highly expressed in various tumor tissues and is associated with poor prognosis of cancer." (PMID 37699892, 2023). "The glutamine transporter SLC1A5, is frequently up-regulated in the tumor cells, and its overexpression is associated with a poor prognosis in cancer patients." (PMID 35897036, 2022). "Here, we found that tumor-bearing caused an increase in the plasma glutamine level and tumor expression of SLC1A5, SLC7A5, and that glutaminase was further elevated in obese mice." (PMID 32121098, 2020). "A variant isoform of SLC1A5 was shown recently to be involved in mitochondrial glutamine uptake in human tumor cells." (PMID 32793601, 2020).